CCL20 (C-C motif chemokine ligand 20)
Diseases named in the same sentence as CCL20 in open-access papers (continued):
Sharing a sentence is not in itself a finding about the gene and the disease.
tumor (continued). "When tumor reached the volume of 300-400 mm3, mice were treated with CCL20-blocking antibody alone or in combination with immune check point blockade (anti-PD-1)." (PMID 36750562, 2023). "We next utilized single-cell transcriptomic data to gain insight on the mechanism by which senescent tumor cells and CCL20 suppress antigen presentation and APC functions." (PMID 37398643, 2023). "Evidence shows that CCL20 accelerates tumor metastasis through both the induction of EMT (Epithelial-to-Mesenchymal Transition) and inhibition of T-cell proliferation and promoted the expansion of immunosuppressive Treg cells." (PMID 35308139, 2022). "The increased numbers of DCs within the tumor were related to CCL20, which is a signature chemokine of Type 17 T cells." (PMID 35459193, 2022). "Previous studies have reported that JAK2/STAT3 pathway regulated the expression of CCL20 and tumor angiogenesis." (PMID 35642002, 2022). "The RANK/RANKL axis induces the secretion and expression of CCL20 in EC cells, which promotes tumor progression and metastasis by EMT." (PMID 35408440, 2022). "Mice fed with VSL#3, a probiotic mixture inducing SCFA production in the intestine had fewer tumor foci in the lungs due to elevated expression of C-C motif chemokine ligand 20 (CCL20) in the airways and enhanced infiltration of Th17 cells." (PMID 35591998, 2022). "Co-stimulation of tumor cells with CCL20 and CXCL8 decreases circ_0026344 expression and facilitates the proliferation, metastasis, and EMT of CRC." (PMID 35935996, 2022). "These consistent expressions support the theory that CCL20 is a proinflammatory cytokine which is excreted by tumor cells and involved with early tumor progression." (PMID 36387204, 2022). "Tregs are recruited through the binding of CCR4 on Tregs surface and CCL22 released by GBM tumor cells and CD163+ TAMs, induced by tumor-derived CCL20 and osteoprotegerin." (PMID 35269652, 2022). "In brief, CCL20 is harnessed by tumor cells to establish an immunosuppressive tumor microenvironment in favor of its survival and metastasis." (PMID 35308139, 2022). "The use of a second deconvolution approach, xCell, consistently demonstrated increased macrophage infiltration within the tumor compartment, as well as a correlation between CCL20 and the M1 macrophage gene signature (r = 0.377, P = 0.0152; fig." (PMID 35394843, 2022). "IL-8 and CCL20 are well-known important regulators in NF-κB signaling and have been associated with chemoresistance in CRC and promote tumor progression." (PMID 35269880, 2022). "CCL20 levels (pg/ml) significantly increased in early-stage tumor than in benign cases (median [IQR], 53.02 [22.97–93.43] and 25.64 [13.59–39.32], p=0.045, respectively)." (PMID 36387204, 2022). "We found that CCL20 expression was generally upregulated in tumor tissues of most cancer types compared with tumor-adjacent tissues." (PMID 35864953, 2022). "CircSMARCC1 up-regulates the chemokine CCL20 secretion by sponging miR-1322, which is involved in the crosstalk between tumor cells and TAMs by targeting CCL20/CCR6 signaling to promote progression of PCa." (PMID 36045408, 2022). "Increasing evidence has demonstrated that chemokine CCL20 can modulate the tumor microenvironment through its effects on fibroblasts, macrophages, and some other immune cells." (PMID 36614059, 2022). "bulgaricus OLL1073R-1 (EPS-R1) induced CCR6+ CD8+ T cells in Peyer’s patches and fostered the infiltration of these cells into CCL20-expressing tumor tissues in mouse models." (PMID 36726985, 2022). "CCL20 is capable of attracting immature pDCs into tumor tissues, which tend to induce Treg differentiation and contribute to a tolerant TME." (PMID 34964283, 2022). "Next, IHC results showed a significant up-regulation of CCL20 expression in the lv-circSMARCC1 xenograft tumor group, which is consistent with the results we observed in human PCa tissues." (PMID 36045408, 2022).
tumor (continued). "CCL20 has been reported to indirectly promote tumor progression by recruiting Treg, Th17, and Th22 cells to maintain the development and immunosuppressive microenvironment." (PMID 36684241, 2022). "Numerous studies have indicated that CCL20 derived from macrophages activates the expression of CCR6 in several tumor cells and then induces cell proliferation and migration, as well as EMT." (PMID 35841069, 2022). "Together, our results imply that Type17 cells secrete CCL20 to mediate DC migration to the tumor, resulting in increased secretion of CXCL10 by DCs in the tumor." (PMID 35459193, 2022). "CCL20 was reported to promote cancer by directly enhancing cancer cell proliferation or indirectly remodeling the tumor microenvironment." (PMID 36009523, 2022). "One of the most important function of CCL20 in the tumor microenvironment is the infiltration of various cell types." (PMID 35408440, 2022). "Both tumor and stromal cells produce CCL20, which, together with its receptor CCR6 (C-C chemokine receptor 6), is involved in leucocyte migration and inflammation." (PMID 36699667, 2022). "CCL20 can also recruit immune cells, such as DCs and Tregs, which further connect CCL20 with the tumor microenvironment." (PMID 36147484, 2022). "We established A549 and H358 cell lines with CCL20 knockdown to explore how CCL20 promotes tumor progression in vitro and in vivo experiments." (PMID 35864953, 2022). "Tumor CCL20 expression was significantly correlated with increased M0 and M1 macrophage fractions (r = 0.458, P = 0.00293 and r = 0.377, P = 0.0164, respectively) in the microenvironment." (PMID 35394843, 2022). "Fifteen distinct clusters were identified and five clusters (M_C1_PLTP, M_C3_CCL20, M_C4_CXCL10, M_C5_NBEAL1, and M_C12_CD207) were abundant in tumor." (PMID 35102420, 2022). "Another study found that obesity-induced IL-6 shifts macrophage polarization toward tumor-promoting macrophages, namely, M2 type, which produces CCL-20 in the CAC microenvironment." (PMID 35935996, 2022). "CCL20 produced in tumor tissues attracts circulating dendritic cells to TME, and more dendritic cells promote T cells' activation and killing ability, leading to tumor regression." (PMID 35864953, 2022). "Following our earlier observations of elevated CXCL11 and CCL20 transcripts in the tumor epithelial compartment, we observed a positive correlation with the expression of their respective receptors, CXCR3 and CCR6, in the microenvironment." (PMID 35394843, 2022). "To thoroughly survey the landscape of CCL20 expression in cancer, we compared the expression level of CCL20 in tumor tissues and tumor-adjacent tissues of pan-cancer using the RNA-seq data from TCGA pan-cancer datasets." (PMID 35864953, 2022). "In turn, neutrophils secrete numerous chemokines, such as CCL2 (MCP-1) and CCL3 (MIP-1), CCL19, and CCL20, to attract monocytes and dendritic cells into the tumor microenvironment." (PMID 36111233, 2022). "It has recently been reported that CCL20 in tumor-bearing mice can turn a cold tumor into a hot tumor, and promote tumor cell elimination." (PMID 35682983, 2022). "In a case study of chemotherapy resistance to the FOLFOX regimen, CCL20 secreted by tumor cells was able to facilitate Tregs recruitment into the TME, which enhanced chemoresistance and closely correlated with poorer survival rates." (PMID 35702353, 2022). "CCL20 can be released in both autocrine and paracrine ways in PC to recruit TAMs followed by cytotoxic T cells suppression and tumor progression via CCR6 receptor." (PMID 35957897, 2022). "In this work, CCL20 was found to be highly expressed mainly in branch II and concentrated in tumor cells." (PMID 35480896, 2022). "It is shown that CLEC7A, VCAN, and KYNU were significantly upregulated in monocytes, BIRC3 and SOD1 were mainly distributed in T cells, CCL20 was highly expressed in tumor cells, and CD69 was highly expressed in B cells." (PMID 35480896, 2022).
tumor (continued). "It was notable that the IL11-induced secretome comprises key factors of the senescence associated secretory phenotype (SASP), including IL6, IL8 and CCL20, which are also important in the tumor microenvironment." (PMID 36012165, 2022). "In this study, we performed bioinformatics analysis, in vitro experiments, and established animal models to confirm the tumor-promoting effects of CCL20 on LUAD." (PMID 35864953, 2022). "Meanwhile, CCL20 produced by tumor-promoting macrophages promotes CAC progression by recruiting CCR6+ B cells and γ δ T cells." (PMID 35935996, 2022). "Except for CXCL8 and CCL20, all hub genes have significantly lower expression in advanced tumor stages." (PMID 36003333, 2022). "Herein, we sought to elucidate the interplay between tumor-derived CCL20 and neutrophils, emphasizing how such interactions suppress antitumor immunity of the host via PD-L1+ neutrophils." (PMID 34519637, 2021). "These suggest that although HuR can upregulate the expression of CCL20, they exhibit a synergetic effect on tumor behavior." (PMID 34569432, 2021). "This study showed that the expression of CCL20 in the tumor was positively correlated with the number of tumor-infiltrating regulatory T cells." (PMID 34638361, 2021). "Researchers have used NK92 cells to bring drug-loaded nanoparticles to a solid tumor and block inhibitory signals in the TME, and local delivery of chemoattractants such as CCL20 or CXCL16 can increase tumor infiltration by ILCs." (PMID 33968039, 2021). "In a recent study, silencing CCL20 in tumor conditioned media from MDA-MB-231 cells attenuated the recruitment of macrophages into tumor-bearing mice." (PMID 34569432, 2021). "In several solid tumors, CCL20 has been identified to potentiate the migration and invasion of tumor cells." (PMID 34569432, 2021). "More interestingly, these observations have been noted in gastric and thyroid cancers where CCL20 enhanced the migration and invasion of tumor cells through MMPs." (PMID 34569432, 2021). "The synergistic effect of CCL20 and other factors in the tumor microenvironment have also been discussed." (PMID 34569432, 2021). "Collectively, these results indicated that tumor-derived CCL20 activated and induced PD-L1 expression on neutrophils." (PMID 34519637, 2021). "In a reciprocal manner, accumulation of CCL20 can further stimulate NF-κB signaling thus forming a feedforward loop to promote cancer stemness and drive tumor progression." (PMID 33483477, 2021). "According to a mechanistic study, tumor derived CCL20 induces the infiltration of immature dendritic cells with two distinct phenotypes that differ in their capacity to activate T lymphocytes." (PMID 34569432, 2021). "Consistent with in vitro and Luminex assays results, tumor tissues derived from LN229 ADO-Cas9 cells displayed conspicuously lower levels of CCL20 and CCR6 compared to the control group." (PMID 33483477, 2021). "Herein, our in vitro study proved that both recombinant human CCL20 and tumor-derived CCL20 can induce PD-L1 expression on neutrophils, thus revealing tumor-derived CCL20 as a regulator of PD-L1 expression." (PMID 34519637, 2021). "CCL20, MMP14, and PCDH7 were upregulated in LUAD tumor tissues and linked to poor clinical outcomes, while BTG2, CD69, GPC3, IL7R, and NMUR1 are the opposite." (PMID 34881236, 2021). "Local injection promoted activation of the CCL20/CCR6 pathway in the tumor microenvironment and further elevated the expression of several molecules related to lymphocyte activation." (PMID 34966384, 2021). "Tumor-derived CCL20 activated by F. nucleatum not only increases CRC metastasis, but also participates in the reprograming of the tumor microenvironment." (PMID 34632963, 2021). "As a possible candidate biomarker, we also reviewed signal pathways and other factors in the tumor microenvironment regulating the tumor-promoting functions of CCL20." (PMID 34569432, 2021).
tumor (continued). "In BM+ tumor cells CCL20 exhibited a dramatic increase, while cytokines/chemokines such as CCL8, IL-6, and tumor necrosis factor superfamily members also showed an increasing trend." (PMID 34222020, 2021). "Overexpression of CCL20 has also been observed in NPC tumours and in the serum of NPC patients and found to be an unfavourable prognostic marker." (PMID 34956172, 2021). "The role of the CCL20/CCR6 pathway in tumor immunity is a controversial topic in light of current known studies." (PMID 34966384, 2021). "This study was aimed at assessing how tumor-derived CCL20 activated neutrophils into TANs and how these TANs inhibited T cell immunity through PD-L1 pathway." (PMID 34519637, 2021). "Beyond the direct role of CCL20 in influencing tumor progression, several studies have highlighted the synergistic effect of CCL20 and other cytokines in promoting tumor progression." (PMID 34569432, 2021). "It was observed that the viability of neutrophils was significantly decreased (P < 0.001), suggesting that tumor-derived CCL20 can activate neutrophils infiltrating the tumor microenvironment." (PMID 34519637, 2021). "Recently, studies have shown that CCL20 promotes tumor progression by remodeling the functions and phenotype of immune cells infiltrated into the tumor microenvironment." (PMID 34519637, 2021). "Our study found that F. nucleatum enhances tumor-derived CCL20 expression and recruits F4/80+ CCR6+ macrophage in the TME." (PMID 34632963, 2021). "CCL20 derived from tumor cells interacts with CD19CD5 B cells overexpressed by CCR6 to promote the development of HCC, possibly through enhanced angiogenesis." (PMID 34869376, 2021). "Studies have shown that CCL20 derived from tumor cells interacts with CD19CD5 B cells overexpressed by CCR6 to promote the development of HCC, possibly through enhanced angiogenesis." (PMID 34869376, 2021). "EBNA1 also enhanced the production of CCL20, which is also important for Treg migration.Tumours with higher density of Treg infiltration correlate with EBNA1 expression and found to have a poorer survival." (PMID 34956172, 2021). "In colitis-associated colorectal cancer, signaling through obesity-induced IL-6 was reported to shift macrophage polarization towards a tumor-promoting phenotype that produced the chemokine CC-chemokine-ligand-20 (CCL-20) in the tumor microenvironment." (PMID 33987528, 2021). "Despite the limited evidence in this area, a better understanding of the communication between CCL20 and other factors in the tumor microenvironment will provide insights into tumor biology." (PMID 34569432, 2021). "On the other hand, an accumulating body of evidence indicates that the CCL20/CCR6 axis regulates endothelial behaviors related to tumor angiogenesis." (PMID 34774095, 2021). "IL17RB activates multiple chemokine (such as CCL20/CXCL1/IL8/TFF1) expressions to enhance tumor cell invasion, macrophage, and endothelial cell recruitment at primary sites and cancer cell survival at distant organs." (PMID 34724890, 2021). "Taken together, our report suggests that the activation of neutrophils by tumor-derived CCL20 is necessary to suppress and impair the antitumor immunity." (PMID 34519637, 2021). "One mice study showed IL-6 shifts macrophage polarization towards tumor-promoting, CCL-20 producing, macrophages." (PMID 34574641, 2021). "Macrophages secrete a large number of chemokines such as CC-like chemokines CCL22 and CCL20, which induce Tregs to recruit to the tumor site, similarly DCs also induce Treg generation, and then promote the metastasis of cancer cells." (PMID 33306121, 2021). "Coincidentally, we also showed that the expressions of CCL5 and CCL20 were appreciably increased in HCC tumor tissues compared to adjacent tissues by immunohistochemistry." (PMID 34938730, 2021). "We also examined the mRNA level of CCL20 in 23 pairs of fresh PC tissues and adjacent non-tumor tissues (AT) using real-time PCR." (PMID 33123272, 2020).
tumor (continued). "Next, we analysed the expression of CCL20 in a breast cancer tumour tissue microarray containing tumour tissues from 40 different patients suffering from ductal breast cancer for which follow-up data were available." (PMID 32601464, 2020). "In conclusion, we observed robust enhanced expression of CCL20 in the majority of tested cancer cell lines and tumour samples compared with the corresponding benign precursor cells." (PMID 32601464, 2020). "CCR6 interacted with CCL20 in the pCR group and is a receptor of CCL20; overexpression of CCL20 augments mitogen-activated protein kinase and protein kinase C signalling, resulting in tumour progression." (PMID 33138797, 2020). "In summary, we demonstrate that EGFR/Ras-induced CCL20 is a chemokine with a vital function in tumour–stroma interaction within the tumour micromilieu." (PMID 32601464, 2020). "The result showed that the mRNA levels of CCL20 were considerably higher in PC tissues than in matched adjacent non-tumor tissues (P<0.001)." (PMID 33123272, 2020). "The effects of EGFR/Ras on the expression and translation of CCL20 were analysed in a large set of epithelial cancer cell lines and tumour tissues by RT-qPCR and ELISA in vitro." (PMID 32601464, 2020). "One study has shown that transplanting human melanoma cells into humanized mice and administering human CCL20 every 3 days double tumor growth." (PMID 32707869, 2020). "To decipher the FDPS‐Wnt/β‐catenin‐CCL20 axis in vivo, we performed immunohistochemistry analysis in the tumour tissues from syngeneic mouse model." (PMID 32596949, 2020). "Taken together, these data demonstrate that CCL20 expression correlates to ERK activation, and that tumours expressing high levels of CCL20 have a more aggressive phenotype." (PMID 32601464, 2020). "CCL20 neutralizing antibody treatment decreased FDPS‐induced tumour growth and macrophage infiltration." (PMID 32596949, 2020). "Coculture of HCC cells with autologous Th9 cells results in upregulation of CCL20 expression on tumor cells in vitro." (PMID 32228589, 2020). "As demonstrated by the in vitro and in vivo model, atypical keratinocytes expressed CCL20 in tumor lesions of cSCC, while normal keratinocytes at the marginal zone of the tumor did not express CCL20." (PMID 33178182, 2020). "Here we show that EGFR/Ras signalling in tumour cells induces the production of CCL20 in a variety of types of cancers." (PMID 32601464, 2020). "Initial priming was shown to involve modulation of DC function in a CT26 colon carcinoma model, with CpG-ODN treatment shown to induce the expression of CCL20 in the tumour, attracting large numbers of circulating DCs into the tumour mass." (PMID 33352882, 2020). "This notion is further corroborated by the observations in patients, where high CCL20 expression correlated with larger and more advanced tumours." (PMID 32601464, 2020). "B16/F10 tumour cells, which express Ccl20, were subcutaneously injected into the right flank of wild-type and Ccr6-deficient C57BL/6 mice." (PMID 32601464, 2020). "On one hand, Th17 cells are able to secrete various cytokines and chemokines, such as IL17, IL23, CCL20 which promote tumor growth." (PMID 32582698, 2020). "A dramatically higher expression of CCL20 was detected in FOXO1(+) tumor cells, suggesting CCL20 was the downstream factor that was responsible for the recruitment of M2 macrophages." (PMID 33052231, 2020). "The recruitment of CD31+ vessels into Matrigel plugs supplied with Ccl20 and injected into mice, which was abrogated when plugs were injected into a Ccr6-deficient mouse strain, further substantiates an angiogenic role for CCL20 in the tumour microenvironment." (PMID 32601464, 2020). "Among these chemokines and cytokines, we selected CXCL8, CCL2, CXCL10, and CCL20 for further study because of their critical role in cell infiltration into the tumor microenvironment." (PMID 32971847, 2020).